IL13 (interleukin 13)
Diseases named in the same sentence as IL13 in open-access papers (continued):
Sharing a sentence is not in itself a finding about the gene and the disease.
emphysema (continued). "Separately, IL-13 mRNA was shown to positively correlate with airway obstruction (FEV1 and FEV1/FVC) and impaired gas exchange and levels were lower in the lungs of patients with severe emphysema." (PMID 35280870, 2022). "Another study using IL-13 overexpression in transgenic (TG) mice described the induction of MMP-2, MMP-9, MMP-12, MMP-13, and MMP-14; cathepsins such as B, S, L, H, and K, involved in emphysema development and increased lung inflammation." (PMID 35740358, 2022). "In transgenic mice overexpressing IL-13, matrix metalloprotease (MMP)- 2, -9, -12, -13, and -14, and cathepsins B, L, S, H, and K were upregulated and treatment with MMP and cysteine proteinase antagonists significantly decreased the emphysema." (PMID 28076408, 2017). "Although the mucus hypersecretion response is not well recapitulated in rodents, a direct role of IL-13 in CS-induced emphysema has been demonstrated." (PMID 25962837, 2015). "The production of IL-10 and IL-13 in this large cohort further did not correlate with the severity of emphysema or airway obstruction (Figure A2 in Appendix)." (PMID 22969766, 2012). "Although IL-17 response to EFs persisted in the emphysema group, there was no increase in response and as expected, there were no discernable changes in IL-10 or IL-13 responses in either group (data not shown)." (PMID 22969766, 2012). "Furthermore, IL-13 could promote alveolar macrophage elastase (MMP-12) upregulation, thus leading to emphysema." (PMID 34621758, 2021). "Moreover, disruption of the IL-13 but not IFN-γ gene prevented emphysema and pulmonary inflammation in IL-18 Tg mice." (PMID 23382928, 2013). "Moreover, disruption of the IL-13 gene but not the IFN-γ gene prevented emphysema and pulmonary inflammation in SPC-IL-18 Tg mice." (PMID 21915293, 2011). "We have previously reported a positive correlation between increase in IFN-γ and IL-10, but not IL-4 or IL-13, responses to EFs from CD4+ T cells isolated from former smokers with emphysema severity." (PMID 22969766, 2012). "Moreover, disruption of the IL-13, IL-17 gene, but not the IFN-γ gene prevented emphysema and pulmonary inflammation in IL-18 Tg mice." (PMID 23382928, 2013).
Arthritis (38 papers, 2005 to 2026). Inflammation of a joint. "An in vivo mouse study showed that local gene transfer of IL-13 was capable of reducing severe cartilage destruction by decreasing MMPs, IL-1 and preventing loss of aggrecan in an immune-complex-mediated arthritis model." (PMID 34360771, 2021). "Functionally, activation of the STAT6 pathway by IL-4/IL-13 plays a critical role in mitigating and resolving immune activation associated with arthritis." (PMID 27273006, 2016). "IL-13 was locally overexpressed in knee joints after injection of an adenovirus encoding IL-13 (AxCAhIL-13), 1 day before the onset of arthritis; injection of AxCANI (an empty adenoviral construct) was used as a control." (PMID 15743487, 2005). "Additionally, both IL-4 and IL-13 have been consistently associated with arthritis and implicated in the downregulation of the inflammatory process, thereby associated with reduced pain in one literature review." (PMID 40649738, 2025). "Osteoclast differentiation, bone loss and cartilage damage were significantly diminished after N. brasiliensis infection but not in the respective mutant mice, suggesting that control of arthritis by the IL-4/IL-13/STAT6 pathway is associated with substantial protection from joint damage." (PMID 27273006, 2016). "In mice, treatment with IL-13 reduced both the severity and incidence of arthritis, demonstrating anti-inflammatory properties previously shown in macrophages." (PMID 39596150, 2024). "The functional enrichment analysis of 132 unique DCEGs in the purple module derived from AECs dataset enriched in key biological functions such as IL-13 Signaling, role of IL-17A in arthritis, glutamate removal from folates, histamine biosynthesis." (PMID 37438356, 2023). "Helminth infection by Nippostrongylus brasiliensis, which robustly induced Th2 cells and accumulated eosinophils, reduced a TNFtg arthritis mice model by IL-4/IL-13-induced STAT6 signaling." (PMID 35163028, 2022). "Key type 2 cytokines, like interleukin (IL)-4 and IL-13, but also others such as IL-5, IL-9, IL-25, and IL-33, exert regulatory properties on arthritis, dampening inflammation and inducing resolution of joint swelling." (PMID 35163028, 2022). "The induction of IL-4/IL-5/IL-13(+) ILC2s mitigated arthritis, suggesting the inflammation is regulated by ILC2s." (PMID 35163028, 2022). "In CIA mice, the severity and the incidence of arthritis were suppressed by the treatment of IL-13, and IL-13 exhibited anti-inflammatory properties on arthritis." (PMID 35163028, 2022). "Regarding the effect of ILC2s on the initiation phase of arthritis, IL-4(+)/IL-5(+)/IL-13(+) ILC2 numbers are increased from the beginning of arthritis in mice." (PMID 35163028, 2022). "STAT6 can be activated by IL-4 and IL-13, mainly regulates Th2 differentiation, and inhibits arthritis and inhibits osteoclast differentiation." (PMID 35002715, 2021). "Human studies exploring the therapeutic potential of IL-4 and/or Il-13 cytokines in arthritis are required, as a boosting of anti-inflammatory cytokines seems to be a very promising approach in arthritis." (PMID 34831223, 2021). "STAT6 plays an essential effect in the differentiation process of Treg cells and can be activated by IL-4 and IL-13 to induce the polarization of macrophages, which is crucial in alleviating the immune activation of arthritis." (PMID 35002715, 2021). "At the molecular level, the attenuation of arthritis is dependent on IL-4/IL-13 secretion and STAT6 signalling pathway in haematopoietic cells." (PMID 27273006, 2016). "Treatment with Th2 cytokines (IL-4, IL-10, and IL-13) was tested in many animal models of arthritis based on the Th1 bias of T cells, showing considerable promise." (PMID 27579330, 2016). "Krill oil consumption was shown to inhibit the progression of arthritis in an experimental mouse model of arthritis, in which the increase of inflammatory cytokines, IL-1 and IL-13, was suppressed." (PMID 27701428, 2016).
Arthritis (continued). "The affected 5q LOH interval harbors several cytokine genes (including IL-3, IL-4, IL-5, IL-13, and CSF2), a gene associated with arthritis susceptibility (SLC22A4), a DNA repair gene (RAD50), and a gene that promotes Type 1 interferon responses (IRF1)." (PMID 25107306, 2014). "IL-5 and IL-13 are cytokines related to arthritis suppression, while tissue-destructive cytokines IL-1β and IL-6 induce Th17 cells and promote osteoclastogenesis." (PMID 24456966, 2013). "Systemic overexpression of IL-13 during collagen-type-II-induced arthritis, in which FcγRIII is also required for arthritis development, decreased joint inflammation." (PMID 15743487, 2005). "Local IL-13 overexpression increased KC concentrations 4- and 18-fold, respectively, at days 3 and 7 after arthritis induction, which correlates with the high amount of PMNs." (PMID 15743487, 2005). "IL-13 overexpression significantly increased the inflammatory cell mass in joint cavity and synovium, by 60% and 30%, respectively, 3 days after arthritis induction." (PMID 15743487, 2005). "Systemic overexpression of IL-13 in collagen-type-II-induced arthritis and local overexpression of IL-13 in rat adjuvant-induced arthritis reduced joint inflammation and bone destruction." (PMID 15743487, 2005). "The proinflammatory action of IL-13 found in the present study seems to be dependent on costimulation with ICs to trigger arthritis onset, since local overexpression of IL-13 during T-cell-mediated rat adjuvant-induced arthritis diminishes joint inflammation." (PMID 15743487, 2005). "Therefore, it is necessary to investigate the IL-13 levels in the synovial fluid from KOA patients and to conduct in vivo animal studies to determine if intraarticular administration of the same level of IL-13 induces arthritis." (PMID 38711706, 2024). "Activated ILC2S and Th2 cells both produce powerful anti-arthritis cytokines IL-4 and IL-13." (PMID 35928276, 2022). "Results obtained from animal, as well as ex vivo, models of arthritis suggest that the IL-4/IL-13 anti-inflammatory properties might be beneficial in the context of inflammatory arthritis treatment." (PMID 34831223, 2021). "Anti-inflammatory cytokines, like IL-13 and IL-4, that were also induced by Zymosan may contribute to tissue repair and quenching of arthritis within 1–2 weeks." (PMID 33878143, 2021). "Finally a local overexpression of several cytokines/adipocytokines poorly described in arthritis (IL-13, IL-18, leptin) was observed." (PMID 22414623, 2012). "While IL-17 is pro-osteoclastogenic in arthritis, IL-4 and IL-13 inhibit osteoclastic differentiation by activation of receptors that decrease RANK formation and by activation of receptors on osteoblasts that decrease RANKL expression but increase osteoprotegerin formation." (PMID 21294892, 2011). "IL-13, a T helper 2 (Th2) cytokine abundantly found in synovial fluid of patients with rheumatoid arthritis, has been shown to reduce joint inflammation and bone destruction during experimental arthritis." (PMID 15743487, 2005). "Local IL-13 overexpression during IC-dependent arthritis enhanced joint inflammation." (PMID 15743487, 2005). "Additionally, it had been suggested that IL-13 might inhibit the development of arthritis in animal models, and that an increase in production of IL-13 significantly correlates with a reduction in pro-inflammatory cytokines." (PMID 23936416, 2013). "The mice were injected with anti-IL-4, IL-5 or IL-13 blocking monoclonal antibody (mAb) on day 3 before (−3d) and day 3 after (+3d) the second immunization with CII, and the incidence of arthritis was monitored." (PMID 27812008, 2016). "IL-4/IL-13-mediated activation of the STAT6 pathway is also critical to protect bone and cartilage during arthritis." (PMID 27273006, 2016). "The inhibitory effect of IL-13 was still present at day 7 after arthritis induction, as only 10% VDIPEN expression was found in the IL-13 group compared to 25% in the control group." (PMID 15743487, 2005).
Arthritis (continued). "In addition, a high level of IL33 induces the expression of inflammatory cytokines IL1-β, IL6, IL13, and IL17, as well as matrix metalloprotease- (MMP-) 3 and MMP-9 in arthritis." (PMID 34305456, 2021). "In line with these human data, genetic deletion of ILC2 in mice aggravated K/BxN serum-induced arthritis whereas expansion of ILC2 by IL-25/IL-33 mini-circles or adoptive transfer of ILC2 from wild-type but not IL-4-/-IL-13-/- mice attenuated arthritis." (PMID 34733292, 2021). "In our study of K/BxN serum-induced arthritis, IL-12 p40 levels had not been different, and IL-6 and M-CSF levels tended to be altered in tg mice in comparison to WT mice (IL-1α and IL-13 levels were not determined)." (PMID 24491163, 2014). "ROS deficient mice are more susceptible to various arthritis models, regardless of the model is mediated by a TH1 (with IFN-γ), TH17 (with IL-17 and IL-23) or even a TH2/IL-13 (with IL-4 and IL-13) type of immune response." (PMID 24358335, 2013). "However, SF from patients with early arthritis display increased Th2 cytokines, such as IL-4 and IL-13, but not Th1-related IFN-γ." (PMID 35925523, 2022). "Zymosan caused systemic inflammation with a marked elevation in multiple pro- and anti-inflammatory cytokines TNF-α, IFN-γ, IL-13, G-CSF, M-CSF, IL-6, IL-18, IL-1α and IL-4 in arthritic rats (all arthritis groups pooled) versus the non-arthritic controls (0.001<p<0.05)." (PMID 33878143, 2021). "The role played by the cytokine receptor IL-13 receptor α1 in arthritis has not been established, but its ligand, IL-13, has been described as a cytokine with anti-inflammatory properties in arthritis and was the target of experimental gene therapy experiments." (PMID 15987489, 2005). "The levels of IL-2, IL-12p40, IL-12p70, and IL-15, as well as those of IL-10 and IL-13, did not increase in the setting of CFA-induced arthritis." (PMID 36293292, 2022).
lung diseases (36 papers, 2010 to 2026). "With bulk RNA-seq, we then investigated the transcriptional activity of LIGHT in human pulmonary fibroblasts compared with interleukin (IL)-13 and IL-17, two other cytokines linked to lung disease." (PMID 40972652, 2025). "Th2 cells mainly produce interleukins (IL)-4, IL-5, and IL-13, which promote eosinophil recruitment and contribute to the development of Th2-associated lung disease." (PMID 40026847, 2025). "Both IL-5 and IL-13 have assumed to be related to pathological responses, and have been linked to the development of lung diseases." (PMID 29107999, 2017). "Th2 cytokines IL-4 and IL-13 have been implicated in altered lung function in various pulmonary disease models and in promoting airway goblet cell hyperplasia." (PMID 21660239, 2011). "An intriguing possibility is that a human genetic variant in the IL13 promoter, previously linked to an increased risk of smoking-related lung disease, may affect nicotine addiction and consumption." (PMID 40775068, 2026). "In addition, studies have found that polymorphisms in IL-13, the endogenous ligand of IL-13Rα1, have been associated with an increased risk of smoking-related lung diseases, possibly due to higher cigarette consumption in affected individuals." (PMID 40775068, 2026). "Also, some cytokines, for instance IL-4 or IL-13, which are implicated in various lung disorders, also behave as inducers of arginase." (PMID 28974751, 2017). "Moreover, increased M2 macrophage infiltration in lung is observed in IL-13-associated lung diseases and IL-13 has been shown to independently enhance the M2 macrophage phenotype in vitro." (PMID 28680858, 2017). "By combining IL-4 and IL-13, we created a more comprehensive model that reflects the complexity of inflammatory processes in lung diseases." (PMID 40370530, 2025). "In lung disease, high levels of IL-10 and IL-13 have been found to cause T- and B-cell–rich inflammatory response, subepithelial fibrosis, and mucus metaplasia with goblet cell hyperplasia and mucin hypersecretion, all of which may be the result of IL-10–induced IL-13 production." (PMID 38508309, 2024). "The JAK/STAT pathway is activated by a variety of pro-inflammatory cytokines, such as IL-6, IL-11, and IL-13, which are upregulated in different lung diseases." (PMID 36793900, 2023). "Among these Th2 cytokines, IL-4 and IL-13 particularly promote fibrosis, and indeed, IL-4 and IL-13 levels are increased in many lung diseases." (PMID 36016937, 2022). "Among these, IL-5, IL-17, IL-13, IL-23, and IL-6 are pro-inflammatory cytokines upregulated in patients with pulmonary diseases." (PMID 35806353, 2022). "Type 2 cytokines, especially IL-4 and IL-13, are elevated in many lung diseases with fibrosis, with IL-13 being recognized as having a more prominent role and serving as an attractive drug target for the diseases." (PMID 29872441, 2018). "Eotaxin and IL-13 are chemokines principally recruiting eosinophils, a component of the inflammatory exudates in asthmatic lung diseases." (PMID 20729176, 2010). "In summary, we provide evidence of the potential relevance of LIGHT, IL-13, and IL-17 action in shaping pulmonary fibroblast differentiation events that could occur in inflammatory and fibrosing diseases of the lungs." (PMID 40972652, 2025). "For example, gut microbial dysbiosis has been implicated in the pathogenesis of lung diseases through various immune-mediated pathways, including modulation of T helper 17 cell (Th17) responses, CD8 T-cell activity, and interleukin-13 (IL-13), interleukin 25 (IL-25), and prostaglandin E2 production." (PMID 40378019, 2025). "Moreover, NLRP3-derived cytokines (e.g., IL-1β, IL-18) appear to be the main inducers of a cytokine cascade (involving IL-23, IL-17, IL-26, IL-6, IL-13, and IL-5) that is responsible for the development of pulmonary diseases in morbidly obese subjects." (PMID 35806353, 2022).
lung diseases (continued). "Finally, HA was directly induced in the lungs of mice by administration of IL-13, indicating a new role for IL-13 in lung disease." (PMID 34185704, 2021). "IL-13 has been identified as the major driver of tissue repair and fibrosis during sustained type 2 responses induced by allergens, helminths, and fungi, as well as in some lung diseases." (PMID 29872441, 2018). "Activation of the A2BR can also promote the expression or release of pro-inflammatory cytokines such as IL-4, IL-8 and IL-13, which may influence the chronic nature of certain lung diseases." (PMID 20169073, 2010). "Although it is difficult to explain the pathogenesis of lung diseases due to the dysregulation of only one cytokine, the down-regulation of SP-D in response to IL-13 might modify the pathogenesis of various diseases and may also alter the susceptibility to pathogens in patients with these diseases." (PMID 21067601, 2010). "The pre-treatment levels of IL-4 and IL-13, secreted from Th2 cells, were significantly lower in patients with MABC lung disease than in control subjects." (PMID 25295870, 2014). "Precision-cut lung slices from donors without a history of lung disease, tobacco smoking, or vaping were pre-treated with IL-13 for 24 h." (PMID 37448802, 2023). "In an article of 2019, the concentration of IL-13 is raised in COPD and other lung disorders." (PMID 34872453, 2021). "Paired alveolar and airway epithelial cells were isolated from donors without any lung disease, and cultured under submerged or air-liquid interface conditions with or without IL-13." (PMID 29672593, 2018). "Secondly, to investigate whether the pulmonary profile of CD4 + Il13+, CD4 + Ifnγ + and CD4 + Il17+ cell numbers at any of the assay times was, collectively, predictive of later lung disease we performed multiple linear regression analyses on these data." (PMID 25889053, 2015). "While deficiency in IL-33 signaling attenuated infection-induced ILC2 numbers and their production of IL-13 and IL-5 in these studies, it remained unclear, whether ILC2s and their cytokine production significantly contributed to AAM differentiation and the severity of pulmonary disease." (PMID 32117319, 2020).
chronic rhinosinusitis (35 papers, 2017 to 2026). Chronic form of sinusitis. "The pathogenesis of chronic sinusitis is still unclear; however, the nasal cavity and paranasal sinuses are commonly affected by type 2 inflammation, which is caused by Th2 cytokines such as interleukin (IL)-5, IL-4, and IL-13." (PMID 36983684, 2023). "PPIs significantly inhibited IL-13-induced eotaxin-3 expression in nasal epithelium, and patients with chronic rhinosinusitis (CRS) taking PPIs showed lower in vivo eotaxin-3 levels than those not taking PPIs." (PMID 35847037, 2022). "It has been proved that Th2 cells bound to IL-4, IL-5 and IL-13 play the main role in the form of chronic sinusitis with polyps." (PMID 34198970, 2021). "Chronic rhinosinusitis with nasal polyps (CRSwNP) is a subtype of chronic rhinosinusitis characterized by persistent eosinophilic inflammation and activation of the type 2 immune pathway, particularly involving interleukins IL-4, IL-5, and IL-13." (PMID 41281095, 2025). "Because ALOX15 expression depends on IL-4 and IL-13, it has been suggested that dupilumab may counter type 2 inflammation in chronic rhinosinusitis in part by suppressing an IL-4/IL-13/ALOX15 M2 macrophage signaling axis." (PMID 38637492, 2024).